MRPL41 (mitochondrial ribosomal protein L41)
Description:
Component of the mitochondrial ribosome large subunit. Also involved in apoptosis and cell cycle. Has the ability to arrest the cell cycle at the G1 phase, possibly by stabilizing the CDKN1A and CDKN1B (p27Kip1) proteins.
Synonyms: BMRP; MRPL27; RPML27; PIG3; MRP-L27; mL41
Tractability: Small molecule: a structure with a bound ligand is known. PROTAC: ubiquitination databases record sites on it; its protein half-life has been measured.
Gene: Protein-coding gene on chromosome 9 (137,551,879 to 137,552,555, forward strand). Ensembl gene ENSG00000182154.
Subcellular location: Mitochondrion
Subcellular location (Human Protein Atlas): Mitochondria
Pathways (Reactome):
Metabolism of proteins: Mitochondrial ribosome-associated quality control; Mitochondrial translation elongation; Mitochondrial translation initiation; Mitochondrial translation termination
Gene Ontology:
Molecular function: protein binding; RNA binding; structural constituent of ribosome
Biological process: translation; mitochondrial translation
Cellular component: mitochondrial large ribosomal subunit; mitochondrion; ribonucleoprotein complex; mitochondrial inner membrane
Genetic constraint (gnomAD): Loss-of-function variants: 4 observed, 4.45 expected, observed/expected ratio (o/e) 0.9, 90% interval 0.43 to 1.77. That is too few expected variants to judge how well the gene tolerates losing a copy. Missense variants: 161 observed, 169.59 expected, observed/expected ratio (o/e) 0.95, 90% interval 0.83 to 1.08. Synonymous variants: 93 observed, 76.94 expected, observed/expected ratio (o/e) 1.21, 90% interval 1.02 to 1.44.
Homologues: Orthologues: chimpanzee MRPL41 (100% identical), macaque MRPL41 (82% identical), guinea pig MRPL41 (76% identical), mouse Mrpl41 (76% identical), pig MRPL41 (76% identical), rat Mrpl41 (76% identical), rat Mrpl41l1 (75% identical), dog MRPL41 (73% identical), rabbit MRPL41 (72% identical), tropical clawed frog mrpl41 (63% identical), zebrafish mrpl41 (60% identical), Drosophila melanogaster mRpL41 (34% identical), and 1 more.
Diseases named in the same sentence as MRPL41 in open-access papers:
MRPL41 is named in the same sentence as 9 diseases in open-access papers, as found by Europe PMC text mining. Sharing a sentence is not in itself a finding about the gene and the disease. The quoted sentences say what the papers report.
breast carcinoma (2 papers, 2013 to 2025). "MRPL41 is a nuclear-encoded mitochondrial gene whose epigenetic regulation in breast cancer is influenced by estrogen receptor status." (PMID 40002900, 2025). "Detailed understanding of the mechanism through which estrogen and tamoxifen affect MTO1 and MRPL41 transcription is expected to provide new insights into breast cancer progression and suggest new strategies for delaying or reversing this process." (PMID 24160266, 2013). "The present results indicate that the two mitochondrial genes, MTO1 and MRPL41, were differentially regulated in breast cancer such that they showed the opposite response to E2, tamoxifen, and TSA." (PMID 24160266, 2013). "In this study, we examined the regulation of MTO1 and MRPL41 in ER+ and ER- breast cancer cells, and also in cells treated with estradiol (E2) and tamoxifen." (PMID 24160266, 2013). "Moreover, the histone deacetylase inhibitor trichostatin A (TSA) increased MTO1 and MRPL41 expression in ER- and ER+ breast cancer cells, respectively." (PMID 24160266, 2013).
lymphoma (1 paper, 2013). A malignant (clonal) proliferation of B- lymphocytes or T- lymphocytes which involves the lymph nodes, bone marrow and/or extranodal sites.
melanoma (1 paper, 2024). A malignant, usually aggressive tumor composed of atypical, neoplastic melanocytes. "In this frame, ATG4D, ATAD3A, and MRPL41 were the top three genes negatively correlated with GALC expression in the TCGA Skin Cutaneous Melanoma database." (PMID 38474307, 2024).
tumor (9 papers, 2012 to 2025). "In contrast, MRPL41 is expressed at lower levels in various small cell lung cancer cell lines, and its downregulation is associated with tumor progression." (PMID 40371222, 2025). "For instance, MRPS29 and MRPL41 have been shown to activate caspase-mediated apoptosis and inhibit tumor growth." (PMID 32917280, 2020). "MRPL41 is downregulated in breast and kidney cancer cell lines and in tissues supporting its role as a tumor-suppressor." (PMID 24160266, 2013). "This suggests that MRPL41 may act as a tumor suppressor in lung cancer, and its downregulation could be one of the important mechanisms for tumor malignant transformation." (PMID 40371222, 2025). "Some of the hypermethylated genes in TET2-wt CMML have been directly or indirectly related to cell cycle arrest, tumor suppression or myeloid differentiation (ZIC1, WT1, WNK2, MRPL41, POU4F2)." (PMID 22328940, 2012).
cancer (7 papers, 2013 to 2025). A tumor composed of atypical neoplastic, often pleomorphic cells that invade other tissues. "Still, when sorted by statistical significance, ATG4D, ATAD3A, and MRPL41 are found in less apical positions in the lists of the top 200 genes negatively correlated with GALC expression in the other human cancer data sets investigated here." (PMID 38474307, 2024). "MTO1 was upregulated in ER- cancer types, meanwhile MRPL41 was upregulated in ER+ cancer types, showing an inverse correlation between expression and promoter methylation." (PMID 24160266, 2013). "MRPL41 showed lower CpG methylation but higher expression in ER + cancer tissues than in ER- cancer tissues." (PMID 24160266, 2013). "However, some cancer types and cells exhibit decreased level of MRPL41." (PMID 29531015, 2018). "However, the results revealed no statistically significant expression difference between cancer tissues and normal tissues for both MTO1 and MRPL41." (PMID 24160266, 2013).
MRPL41 also shares sentences with these, for which no sentence is quoted: colorectal cancer (1 paper); cutaneous melanoma (1); laryngeal carcinoma (1); renal carcinoma (1).